LMNB2 (lamin B2)
Diseases named in the same sentence as LMNB2 in open-access papers (continued):
Sharing a sentence is not in itself a finding about the gene and the disease.
tumor (continued). "We detected higher lamin B2 expression in 20 NSCLC tumor tissues obtained from The Cancer Genome Atlas than in adjacent normal lung tissues." (PMID 29285216, 2017). "Importantly, combinatorial targeting of LMNB2 with Atezolizumab (PD-L1 inhibitor) displayed a synergistic effect on suppressing tumor progression both in vitro and in vivo, particularly in HCC models with SPOP mutations or LMNB2 overexpression." (PMID 40483310, 2025). "Similarly, Atezolizumab mitigated tumor weight differences between the SPOP + LMNB2 + sh-NC and SPOP-M35L + LMNB2 + sh-NC groups, suggesting that SPOP mutations in HCC promote immune evasion partly through LMNB2." (PMID 40483310, 2025). "Besides IHC analysis of tumor tissues revealed that LMNB2 upregulated PD-L1 and downregulated immune markers CD3 and CD8." (PMID 40483310, 2025). "Previous studies have posited that LMNB2 interacts with tumor immune cells, including B cells, CD8+ T cells, CD4+ T cells, and macrophages, and may be implicated in HCC progression." (PMID 40483310, 2025). "However, HCC-associated mutations or pathologically low expression of SPOP lead to aberrant stabilization of LMNB2, which in turn, directly induces PD-L1 transcription, thereby promoting tumor immune evasion of HCC." (PMID 40483310, 2025). "It is known that LMNB2 can also play an important role in tumor development." (PMID 39774004, 2024). "In addition, by mining GSE152048, we further identified the distribution of LMNB2 in tumour microenvironment of SARC." (PMID 39774004, 2024). "A high level of LMNB2 expression showed positively correlation with tumor necrosis and metastasis." (PMID 39774004, 2024). "In addition, the shLMNB2 and shCtrl tumor tissue sections were subjected to immunohistochemical staining, to detect the expression of LMNB2, p21, and the nuclear proliferation marker Ki67." (PMID 33782407, 2021). "Tumor xenograft experiments in nude mice showed that LMNB2 knockdown inhibited tumorigenesis." (PMID 29285216, 2017). "Furthermore, we further studied the role of LMNB2 on tumor growth in vivo (three mice per group)." (PMID 34917510, 2021). "Twenty days after transfected HuH7 cells were injected into nude mice, the volume and weight of formed tumor were significantly smaller than those of control group, also indicating that LMNB2 knockdown could inhibit the growth of HCC cells in vitro and in vivo." (PMID 34917510, 2021). "This study provides the first experimental evidence revealing that NOP2‐dependent m5C modification of LMNB2 mRNA increases the LMNB2 protein expression by enhancing its mRNA stability, thereby facilitating CRC tumor growth and metastasis." (PMID 40366008, 2025). "Results showed that differences in tumor weights among the sh-NC + EV, sh-SPOP + EV, and sh-SPOP+sh-LMNB2 + EV groups were significantly reduced with Atezolizumab treatment, indicating that elevated LMNB2 promotes tumor immune evasion." (PMID 40483310, 2025). "Downregulation of both LMNB2, the target of miR-326 in HCC, and SNHG1 inhibited tumor proliferation and growth in vitro and in vivo." (PMID 34917510, 2021). "Our recent studies demonstrated that some passenger strands of miRNAs, e.g., miR-143-5p, miR-145-3p and miR-150-3p, behave as tumor-suppressive miRNAs in LUAD cells by targeting oncogenes, e.g., LMNB2, MCM4 and TNS4, respectively." (PMID 32932948, 2020). "Immunohistochemical analysis of 150 NSCLC patient samples revealed that both lamin B2 and MCM7 levels positively correlated with histological grade and tumor TNM stage." (PMID 29285216, 2017). "Moreover, both lamin B2 and MCM7 levels correlated with histological grade, and tumor TNM stage." (PMID 29285216, 2017). "In addition, LMNB2 can promote the proliferation and tumor formation of non-small cell lung cancer." (PMID 33782407, 2021).
infection (1 paper, 2026). The state of being infected such as from the introduction of a foreign agent such as serum, vaccine, antigenic substance or organism. "The infection led to a slight downregulation of lamin B2 expression at 8 and 12 hpi, although this was not statistically significant (see also S3)." (PMID 41557685, 2026).
LMNB2 also shares sentences with these, for which no sentence is quoted: Ataxia (2 papers); colon adenocarcinoma (2); Obesity (2); pancreatic adenocarcinoma (2); acanthosis nigricans (1); acquired lipodystrophy (1); adenoid cystic carcinoma (1); Alzheimer disease (1); arrhythmogenic right ventricular cardiomyopathy (1); carcinosarcoma (1); central obesity (1); cholangiocarcinoma (1); endometrial carcinoma (1); Fanconi anemia (1); genetic lipodystrophy (1); head and neck squamous cell carcinoma (1); hypertriglyceridemia (1); kidney chromophobe (1); lung squamous cell carcinoma (1); lymphoid neoplasm (1); melanoma (1); metabolic disorders (1); neurological disorders (1); oligospermia (1); ovarian serous cystadenocarcinoma (1); paraganglioma (1); partial lipodystrophies (1); peripheral neuropathy (1); pheochromocytoma (1); Primary microcephaly (1).
A further 8 diseases each share a sentence with LMNB2 in 1 paper.